OR1F1 (olfactory receptor family 1 subfamily F member 1)
Description:
Odorant receptor.
Synonyms: OLFMF; OR1F10; OR1F4; OR1F5; OR1F6; OR1F7; OR1F8; OR1F9; OR16-36; OR16-37; OR16-88; OR16-89; OR16-90; OR3-145; OR1F13P; ORL1023
Tractability: Antibody: UniProt places it where antibodies can reach, with medium confidence; UniProt predicts a signal peptide or a membrane-spanning region; its Gene Ontology location is reachable by antibodies, with medium confidence.
Gene: Protein-coding gene on chromosome 16 (3,188,204 to 3,224,779, forward strand). Ensembl gene ENSG00000168124.
Subcellular location: Cell membrane
Pathways (Reactome):
Sensory Perception: Expression and translocation of olfactory receptors
Gene Ontology:
Molecular function: olfactory receptor activity; G protein-coupled receptor activity
Biological process: signal transduction; detection of chemical stimulus involved in sensory perception of smell; G protein-coupled receptor signaling pathway
Cellular component: plasma membrane; membrane
Genetic constraint (gnomAD): Missense variants: 493 observed, 390.94 expected, observed/expected ratio (o/e) 1.26, 90% interval 1.17 to 1.36. Synonymous variants: 184 observed, 163 expected, observed/expected ratio (o/e) 1.13, 90% interval 1 to 1.28.
Homologues: Orthologues: macaque OR1F1 (92% identical), chimpanzee OR1F1 (89% identical), rat Or1f26 (79% identical), rat Or1f31 (79% identical), rat Or1f19f (77% identical), rat Or1f27 (77% identical), rat Or1f20e (76% identical), rat Or1f30 (76% identical), rat Or1f29l1 (75% identical), rat Or1f45 (75% identical), rat Or1f20b (75% identical), rat Or1f21 (75% identical), and 8 more. Paralogues in human: OR1J4 (59% identical), OR1C1 (58% identical), OR1J1 (57% identical), OR1E1 (56% identical), OR1E2 (56% identical), OR1N1 (56% identical), OR1N2 (56% identical), OR1G1 (55% identical), OR1J2 (55% identical), OR7D4 (55% identical), OR1L4 (55% identical), OR1L6 (55% identical), and 116 more.
Diseases named in the same sentence as OR1F1 in open-access papers:
OR1F1 is named in the same sentence as 3 diseases in open-access papers, as found by Europe PMC text mining. Sharing a sentence is not in itself a finding about the gene and the disease. The quoted sentences say what the papers report.
Parkinson disease (1 paper, 2019). A progressive degenerative disorder of the central nervous system characterized by loss of dopamine producing neurons in the substantia nigra and the presence of Lewy bodies in the substantia nigra and locus coeruleus. "The results also showed a number of genes that decreased in an Mn dose-dependent manner which include genes involved in iron transport (TF), protective activity of telomeres (TERF2), neurosensory function (MYO15a, OR1F1), and neurological disease such as ADHD (DIRAS2) and Parkinson’s disease (FRK)." (PMID 31396262, 2019).
OR1F1 also shares sentences with these, for which no sentence is quoted: breast carcinoma (1 paper); neurological disease (1).